ENSG00000267059 (novel transcript, readthrough between UQCR11 and MBD3)
Gene: Protein-coding gene on chromosome 19 (1,578,339 to 1,605,445, reverse strand). Ensembl gene ENSG00000267059.
Genetic constraint (gnomAD): Missense variants: 86 observed, 72.59 expected, observed/expected ratio (o/e) 1.18, 90% interval 0.99 to 1.42. Synonymous variants: 34 observed, 32.45 expected, observed/expected ratio (o/e) 1.05, 90% interval 0.8 to 1.39.